TMPRSS2 (transmembrane serine protease 2)
Diseases named in the same sentence as TMPRSS2 in open-access papers (continued):
Sharing a sentence is not in itself a finding about the gene and the disease.
prostate tumors (continued). "The TMPRSS2-ERG fusion is the most frequent rearrangement, being detected in approximately 50% of the prostate tumors." (PMID 21829708, 2011). "The present study was designed to assess the feasibility of an immunomagnetic enrichment method for detecting circulating prostate tumor cells using research prototype TMA assays for prostate-specific mRNAs (PSA, PCA3 and the TMPRSS2:ERG gene fusion)." (PMID 20598135, 2010). "The literature suggests that aggressive prostate tumors frequently demonstrate dysregulation of androgen receptor (AR) signaling, alterations in ETS transcription factors due to TMPRSS2-ERG fusion events, and overexpression of clinically monitored biomarkers such as PCA3." (PMID 41375053, 2025). "Taken together, the results suggested that NSAID treatments decreased epithelial to mesenchymal transition of prostate tumor cells irrespective of the TMPRSS2-ERG fusion state in PCa." (PMID 37894421, 2023). "The Expression Atlas adds the observation that expression levels of TMPRSS2 and SLC45A3 vary across tissue and tumor types but that both TMPRSS2 and SLC45A3 are highly expressed in normal prostate tissues and prostate tumors, as shown in the Expression Atlas Baseline Expression Widget." (PMID 32636365, 2020). "In addition, the coexistence of TMPRSS2-ERG and SLC45A3-ERG rearrangements has been identified in a subset of prostate tumors." (PMID 29088771, 2017). "In prostate tumors, expression of several ABC transporter genes is down-regulated and shows significant associations with clinical variables and the absence of the TMPRSS2-ERG fusion transcript." (PMID 26459268, 2015). "For example, the detection of TMPRSS2-ERG fusion transcript were reported to 73% of primary prostate tumor samples and 43% samples taken from non-malignant tissues." (PMID 24739220, 2014). "Extended analysis of the prostate tumors for which deletion evolution paths were provisionally characterized confirmed the temporal relation between the deletion of PTEN and TMPRSS2-ERG rearrangements (both via deletions and insertions in patient P01-28) in a coherent analysis framework." (PMID 25160065, 2014). "Therefore, prostate tumor cells harboring ETS fusions, such as TMPRSS2-ERG are more prone to robust response to PARPi, alone on in combination with LDR." (PMID 23565244, 2013). "In addition to the common fusion with ERG gene, TMPRSS2 is also fused to several other ETS transcription factor genes, such as ETV1, ETV4, and ETV5, in approximately 10% of prostate tumors." (PMID 24133629, 2013). "We inspected methylation of DNA around the TDRD1 transcription start site in prostate tumors, that we had analyzed by MeDIP-Seq, and found this region to be differentially methylated between tumors with and without the TMPRSS2:ERG gene fusion." (PMID 23555854, 2013). "The most common type of ETS rearrangement, the fusion of androgen-regulated TMPRSS2 with the oncogenic ERG is detected in approximately half of prostate tumors but none of benign glands." (PMID 24098661, 2013). "The Toronto cohort, a subset of that previously characterised for clinical markers, includes 69 patients with TMPRSS2–ERG T1/E4 fusion-positive tumours and 70 prostate tumours that were TMPRSS2–ERG fusion negative." (PMID 20068566, 2010). "Likewise, the TMPRSS2:ERG gene fusion, commonly assessed in platforms like MiPS, arises from AR-driven transcriptional activity and reshapes the transcriptomic landscape of prostate tumors." (PMID 40649790, 2025). "It was also recently determined that ERG (and the common TMPRSS2-ERG rearrangement) activates the transcriptional program regulated by YAP1, and that prostate-specific activation of either ERG or YAP1 in mice induces similar transcriptional changes and results in age-related prostate tumors." (PMID 36979713, 2023).
prostate tumors (continued). "In addition to confirming the presence of recurrent CaP genomic alterations such as TMPRSS2-ERG fusion, PTEN and CHD1 deletions, a novel recurrent deletion of LSAMP gene on chromosome 3q13.31 was found to more prevalent in prostate tumors from AA men compared to CA men (26% vs. 7%)." (PMID 29690565, 2018). "Supporting this hypothesis, PTEN deletion is more common in prostate tumors with TMPRSS2-ERG rearrangements, than in those without, and in mouse models, ERG over-expression results in adenocarcinoma only when accompanied by a second mutation that activates the PI3K/AKT pathway." (PMID 24642271, 2014). "Close inspection of data reveals that in several prostate tumors tested negative for the TMPRSS2:ERG rearrangement, TDRD1 is expressed at high levels despite low ERG expression, suggesting that ERG may not be the only factor which is capable of activating TDRD1 transcription." (PMID 23555854, 2013). "Although TMPRSS2/ERG fusion is detected in approximately 50% of human prostate tumors, ERG transgenic mice do not develop prostate tumor spontaneously." (PMID 27191272, 2016). "TMPRSS2-ERG positive VCaP cells (0, 10, 100, 1,000, 10,000, and 100,000) were incrementally spiked into 1,000,000 LNCaP cells to simulate prostate tumor tissue samples, which contain mixtures of tumor and non-malignant stroma, and 1/10 of each sample was analyzed using PRISM-SRM." (PMID 25889691, 2015).
lung carcinoma (68 papers, 2012 to 2025). "Lower TMPRSS2 expression and higher DNA methylation were linked to negative clinicopathological features and unfavorable outcomes in lung cancer patients." (PMID 40145441, 2025). "Decreased TMPRSS2 expression and increased DNA methylation of TMPRSS2 were associated with various clinicopathological parameters in patients with lung cancer." (PMID 35017320, 2022). "GSEA was conducted to examine the TMPRSS2-associated signaling pathways that were differentially activated in lung cancer." (PMID 35017320, 2022). "Decreased TMPRSS2 related with a poor prognosis and was associated with immune cell infiltration in lung cancer." (PMID 35017320, 2022). "Based on these results, we identified and elucidated the important roles of TMPRSS2 in lung cancer and the underlying mechanisms associated with its immune infiltration." (PMID 35017320, 2022). "So we detected the expression of ACE2 and TMPRSS2 at the resection margin of lung cancer patients to explore the molecular mechanism of lung cancer patients’ high susceptibility to SARS-CoV-2." (PMID 34094930, 2021). "TMPRSS2 expression was negatively associated with 13 lung cancer-related genes and showed a positive correlation with 130 lung cancer-related genes." (PMID 35082790, 2021). "A proposed five-gene diagnostic signature, including KRT5, MUC1, TREM1, C3, and TMPRSS2, as well as an eight-gene classifier for lung cancer subtypes, exhibited a high predictive accuracy of 0.936 during testing on 2556 adenocarcinoma samples and 1630 squamous cell carcinoma samples." (PMID 38612418, 2024). "Notably, the expression of TMPRSS2 displays a significant association with OS in several types of cancers, including brain cancer, colorectal cancer, breast cancer, lung cancer, and ovarian cancer." (PMID 36992839, 2023). "Therefore, TMPRSS2 appears to play an important role in PM 2.5 causing the more severe effects of COVID‐19 and lung cancer." (PMID 36975376, 2023). "Intriguingly, TMPRSS2 expression associated with immune cell infiltration in lung cancer." (PMID 35017320, 2022). "We found that OAS1, ACE2, TMPRSS2 were associated with overall survival of lung cancer." (PMID 35082790, 2021). "Therefore, it is conceivable that a high level of TMPRSS2 may be independently linked to better prognoses of lung cancer." (PMID 36992839, 2023). "This increase was comparable to the TMPRSS2 mRNA levels observed in SARS-CoV-2-infected Calu3 lung carcinoma cells." (PMID 40055791, 2025). "For patients with mild‐to‐moderate COVID‐19, pramipramide has been shown to decrease ACE2 and TMPRSS2 expression in lung cancer cells, prevent SARS‐CoV‐2 from entering host cells, and facilitate faster virus clearance." (PMID 40145441, 2025). "TMPRSS2, essential for viral entry, shows decreased expression in several tumors but acts as a prognostic biomarker in prostate and lung cancers." (PMID 40145441, 2025). "They identified that elevated TMPRSS2 levels in epithelial cells and more intense inflammatory reactions mediated by macrophages were shared pathological traits in both COVID‐19 and lung cancer." (PMID 40145441, 2025). "Bexarotene's ability to influence ACE2 and TMPRSS2 expression offers a novel therapeutic avenue for treating COVID‐19 in lung cancer patients." (PMID 40145441, 2025). "For instance, prolonged exposure to particulate matter 2.5 (PM2.5), a crucial component of air pollution, results in the upregulation of transmembrane serine protease 2 (TMPRSS2) in lung cancer cells." (PMID 38983267, 2024). "Elevated expression of TMPRSS2 was also positively correlated with the advanced overall stages of lung cancer patients (P < 0.05)." (PMID 36975376, 2023). "In two lung cancer cohorts (GSE13213 and GSE4573), higher TMPRSS2 expression was associated to favorable outcomes (OS HR = 0.68, 95% CI = 0.51–0.89, Cox p = 0.006146; OS HR = 0.83, 95% CI = 0.70–0.0.99, Cox p = 0.042151)." (PMID 36992839, 2023).
lung carcinoma (continued). "A higher level of promoter methylation was detected in the early stage, suggesting that the high levels of TMPRSS2 promoter methylation were related to earlier stages of lung cancer development." (PMID 36992839, 2023). "The RNA and protein levels of ACE2 and TMPRSS2 were assessed in lung cancer cell lines 12 h after stimulation with different concentrations (10%, 20%, and 50%) of CSE." (PMID 37428471, 2023). "In this study, we proposed a possible mechanism that explains why TMPRSS2 expression correlates with immune infiltration leads to different prognosis patterns in different types of lung cancer." (PMID 36992839, 2023). "A high level of TMPRSS2 protein was detected in three lung cancer cell lines (H460, A549, and H1975)." (PMID 36975376, 2023). "Depletion of TMPRSS2 in lung cancer cells suppressed anchorage‐independent growth and xenograft tumor growth in mice." (PMID 36975376, 2023). "Correlation of the mRNA expression level of TMPRSS2 in different stage and clinical prognostic potential in lung cancer with different clinicopathological factors." (PMID 36992839, 2023). "To systematically explore the effect of TMPRSS2 on lung cancer cells, we used whole‐transcriptome analysis to analyze the effects of TMPRSS2 overexpression on gene expression." (PMID 36975376, 2023). "To explore the molecular effects of TMPRSS2 on lung cancer cells, we examined the effects of overexpressing TMPRSS2 using H1299 cells, which express low levels of endogenous TMPRSS2." (PMID 36975376, 2023). "The expression levels of TMPRSS2 were found to correlate with nuclear AhR expression and with cancer stage in lung cancer patient tissue." (PMID 36975376, 2023). "The new molecules efficiently inhibit the fusion to the ACE/TMPRSS2-positive cells (H1299, lung carcinoma cells) with a 2-fold increase in potency compared to the initial natural compound." (PMID 37324739, 2023). "In this study, we show that long‐term exposure of lung cancer cells to PM2.5 can activate AhR to promote the expression of TMPRSS2 and IL18 and promote lung cancer progression." (PMID 36975376, 2023). "To evaluate the role of TMPRSS2 expression in lung cancer progression in vivo, we examined the expression levels of TMPRSS2, IL18, and nuclear AhR by IHC in tumor specimens from 25 lung cancer patients." (PMID 36975376, 2023). "A low level of TMPRSS2 was also detected in H1299 lung cancer cells and normal IMR90 fibroblasts but was undetectable in normal MRC5 fibroblasts." (PMID 36975376, 2023). "Kidney epithelial cell line Vero E6, which express high ACE2 and low TMPRSS2 levels, and human lung carcinoma cells Calu-3, which express high TMPRSS2 levels, were used as cell models to test SB activity." (PMID 37324739, 2023). "TMPRSS2 mRNA expression was significantly correlated with most diverse immune cell markers in lung cancer." (PMID 35017320, 2022). "Analysis mining of the UALCAN database revealed that TMPRSS2 expression was reduced in both female and male lung cancer patients." (PMID 35017320, 2022). "The protein level of TMPRSS2 was also much lower in lung cancer tissues than in normal lung tissues." (PMID 35017320, 2022). "In summary, these results demonstrated that TMPRSS2 expression is significantly correlated with clinicopathological parameters in lung cancer patients." (PMID 35017320, 2022). "Analysis of GSE31210 and GSE13213 datasets of PrognoScan revealed considerably poor OS and RFS of lung cancer patients in the down‐regulated TMPRSS2 mRNA expression group relative to their elevated expression counterparts." (PMID 34951103, 2022). "Further studies are required to confirm the prognostic value and mechanism by which TMPRSS2 influences the oncogenesis of lung cancer." (PMID 35017320, 2022). "According to TMPRSS2 expression, lung cancer patients were divided into low- and high-expression groups." (PMID 35017320, 2022).
lung carcinoma (continued). "Lung cancer patients with lower TMPRSS2 expression exhibited poor overall survival (OS), postprogression survival (PPS) and first-progression survival (FPS) according to the Kaplan–Meier plotter database." (PMID 35017320, 2022). "TMPRSS2 expression in 58 and 50 paired LUAD and LUSC samples and corresponding adjacent normal samples was analyzed, and our results suggested a marked decrease in TMPRSS2 in lung cancer." (PMID 35017320, 2022). "With respect to sex, low TMPRSS2 expression was strongly linked with worse OS and FPS in female and male lung cancer patients." (PMID 35017320, 2022). "It has been reported that TMPRSS2 has a key role in many kinds of cancers in vitro and in vivo including breast, colorectal, head and neck, ovarian, stomach and lung cancer." (PMID 34951103, 2022). "First, we did not perform in vitro or in vivo experiments to validate the precise roles and molecular mechanisms of TMPRSS2 in lung cancer." (PMID 35017320, 2022). "In summary, we systematically analyzed the clinical significance and molecular mechanism of TMPRSS2 in lung cancer." (PMID 35017320, 2022). "The results of univariate Cox regression analysis indicated that TMPRSS2 expression, age, T stage, N stage, M stage and radiation therapy were obviously correlated with the OS of lung cancer patients." (PMID 35017320, 2022). "The impact of TMPRSS2 on the survival of lung cancer patients was analyzed with the PrognoScan and Kaplan–Meier plotter databases." (PMID 35017320, 2022). "Subsequently, TMPRSS2 expression was negatively and significantly related with the prognosis of lung cancer patients." (PMID 35017320, 2022). "We then examined the expression profiles of TMPRSS2 in lung cancer based on clinicopathological characteristics." (PMID 35017320, 2022). "Intriguingly, quinine can restrain infection of human cells lines with SARS-CoV-2, especially in TMPRSS2+ human lung cancer cell lines." (PMID 35774410, 2022). "This study was designed to explore the expression status, prognostic significance and molecular functions of TMPRSS2 in lung cancer." (PMID 35017320, 2022). "In our study, we tested the effects of SMYD2 inhibition on TMPRSS2 expression in HT-29 cells and Caco-2 cells, two human colorectal adenocarcinoma cell lines, and Calu-3 cells, one lung cancer cell line." (PMID 35455942, 2022). "The DNA methylation level of the TMPRSS2 promoters showed marked increases in LUAD and LUSC, indicating a potential cellular mechanism of TMPRSS2 gene expression in lung cancer." (PMID 35017320, 2022). "We show that ACE2 is co-expressed with membranous FURIN and/or TMPRSS2 in 16% of our NSCLC patient cohort, making these lung cancer cells susceptible to SARS-CoV-2 infection." (PMID 36077610, 2022). "Calu3 cell line (human lung cancer cell line), as with the airway epithelial cells, express high amounts of TMPRSS2 and SARS-CoV-2 entry into these cells is dependent on TMPRSS2." (PMID 34063247, 2021). "Our work makes a comprehensive evaluation of NRP1 and TMPRSS2 in lung cancers, providing information for drug development and support for COVID-19 patients with lung cancers." (PMID 34168096, 2021). "The proportion of epithelial cells expressing ACE2 and TMPRSS2 was higher at the resection margin of lung cancers than in normal tissues, suggesting that the resection margins of lung cancer tissues were still more susceptible to COVID-19 infection." (PMID 34094930, 2021). "Both are decreased in human lung cancer tissues, consistent with the increased methylation in promoter area and increased microRNAs that target NRP1 or TMPRSS2 in lung cancer tissues." (PMID 34168096, 2021). "The natural substance quinine exerts antiviral activity against SARS-CoV-2 that was comparable to its chemical derivatives, H-CQN and CQN, particularly in TMPRSS2+ human lung cancer cell lines." (PMID 33918670, 2021).